GZMK (granzyme K)
Diseases named in the same sentence as GZMK in open-access papers (continued):
Sharing a sentence is not in itself a finding about the gene and the disease.
cancer (continued). "This investigation highlighted the diverse associations between DNA methylation of GZMA, GZMB, GZMK, and PRF1 and survival outcomes, displaying the potential prognostic implications of epigenetic modifications in immune-related genes across different cancer types." (PMID 40002821, 2025). "Furthermore, our analysis of the association between GZMK, TREM2, and OR4D10 expression and cancer patient prognosis in the TCGA cohort demonstrated that reduced expression of GZMK and increased expression of TREM2 and OR4D10 were significantly correlated with poor prognosis in THCA." (PMID 40332815, 2025). "To determine the prognostic implications of GZMA, GZMB, GZMK and PRF1 across the different cancer types, we explored their Kaplan–Meier plots." (PMID 40002821, 2025). "In summary, the CNV analysis of GZMA, GZMB, GZMK and PRF1 across multiple cancer types highlighted a remarkable prevalence of heterozygous amplifications and deletions compared to homozygous variations." (PMID 40002821, 2025). "Together with our CyTOF results that showed an accumulation of the CD8 TEM GZMK precursor state and terminally exhausted CD8+ T cells in CLL LNs, these findings suggest cancer-driven exhaustion of CD8+ T cells in the lymphatic tissue of patients with CLL." (PMID 40775219, 2025). "As a comprehensive pan-cancer exploration, we next investigated the impact of DNA methylation of GZMA, GZMB, GZMK and PRF1 on survival outcomes." (PMID 40002821, 2025). "Our findings align with those of recent studies emphasizing the significance of immune-related genes, specifically GZMA, GZMB, GZMK and PRF1, in cancer pathogenesis and clinical outcomes." (PMID 40002821, 2025). "In conclusion, our study underscores the multifactorial impact of GZMA, GZMB, GZMK and PRF1 and their potential as biomarkers for personalized cancer immunotherapy." (PMID 40002821, 2025). "First, we looked at the expression of GZMK, TREM2, and OR4D10 in the pan-cancer datasets GTEx and TCGA." (PMID 40332815, 2025). "Following the SNV analysis, we examined the proportion of heterozygous and homozygous mutations (both deletions and amplifications) in GZMA, GZMB, GZMK and PRF1 in the different cancers." (PMID 40002821, 2025). "A pathway analysis was conducted to evaluate the inhibitory and activating effects of ten cancer-related pathways on the expression of GZMA, GZMB, GZMK and PRF1." (PMID 40002821, 2025). "External validation yielded a 4-gene set (GZMK, GZMA, ITGAL, and IL7R); higher gene expression levels predicted better overall survival in The Cancer Genome Atlas cohort (p=0.005)." (PMID 40766148, 2025). "The results demonstrated that a poor prognosis in THCA was substantially correlated with reduced expression of GZMK, TREM2, and OR4D10 (p = 0.041, 0.024, and 0.017), suggesting that GZMK, TREM2, and OR4D10 are the potential oncogenes in this cancer." (PMID 40332815, 2025). "Within the TCGA database, the relative expression levels of GZMK (log2(TPM + 1)) were analyzed in 1,085 BRCA and 112 normal tissue samples, showing significantly higher expression in cancer tissues (P < 0.0001)." (PMID 38833021, 2024). "(M-Q) Phenotype switch (KIR2DL4, GZMK, CD9, CD49a, and PD-1) of NK cells was induced by cell-to-cell interactions with cancer cells." (PMID 39387546, 2024). "As such, promoting transition of GZMK+ CD8+ T cells back to effector-like cells and preventing them from further exhaustion would be a strategy for cancer immunotherapy." (PMID 33429363, 2021). "The expression levels of JUN, SFN, HSPB1, and CD47 in cancer cells and the expression levels of KLRB1, CD48, GZMK, and LY6E in CD8+ T cells were consistent with the scRNA-seq results." (PMID 33083004, 2020). "Similarly, GZMK exhibited high amplification rates in ACC and KIRC, with deletions also observed in cancers like SARC and LUAD." (PMID 40002821, 2025).
cancer (continued). "Additionally, we collected the IC50 values of drugs from various cancers and cell lines from the GDSC and CTRP databases in order to correlate them with GZMA, GZMB, GZMK and PRF1 expression levels." (PMID 40002821, 2025). "Among these, GZMK, TREM2, and OR4D10 have emerged as promising candidates due to their involvement in immune regulation and cellular processes that are often dysregulated in cancer." (PMID 40332815, 2025). "Furthermore, four gene signatures of TEX phenotype, terminal, GZMK+, OXPHOS- and TCF7+ TEX subtypes, were identified from pan-cancer single-cell sequencing data." (PMID 37113755, 2023). "In specific, TIS is referred to as an 18‐gene signature (CCL5, GZMK, CD3D, CD3E, CD2, HLA‐DRA, IL2RG, NKG7, CIITA, CXCR6, LAG3, TAGAP, HLA‐E, CXCL13, IDO1, CXCL10, STAT1, and GZMB), which was related to the response to ICIs in various cancers." (PMID 37434432, 2023). "Thus, an extensive analysis of GZMA, GZMB, GZMK and PRF1 may not only provide a greater understanding of their role in cancer biology, but also reveal their similarities and differences across different cancer types." (PMID 40002821, 2025). "However, many questions are raised about their counterparts that only express GZMK; in our data, these are not cytolytic, have higher basal proliferation in patients with cancer, but do not proliferate after immunotherapy, and adopt a memory phenotype in the periphery." (PMID 40299576, 2025). "In addition, our current understanding of the complete roles of GZMA, GZMB, GZMK and PRF1 are still evolving and other factors may play a role in the varying expression levels of these genes in the context of the different clinical prognoses seen in these cancer types." (PMID 40002821, 2025).
infection (16 papers, 2009 to 2026). The state of being infected such as from the introduction of a foreign agent such as serum, vaccine, antigenic substance or organism. "Based on IL7R, GZMK, mir-93-5p, and mir-345-5p we suggest a novel possible workflow to distinguish infection, where those markers are downregulated, from rejection, where they are overexpressed, on EMB specimens." (PMID 40453097, 2025). "We expected that the main cell source of GzmA in this model to be a component of the innate immune response since reduction of inflammation in GzmA-/- and GzmK-/- mice was observed within the first 24 h after infection." (PMID 34815792, 2021). "WT, GzmA-/- and GzmK-/- mice showed a similar bacterial load in blood and spleen at both 18 and 42 h, time after which some animals had already begun to clear the infection." (PMID 34815792, 2021). "At day 8 after infection significantly more virus-specific CD8+ T cells from the spleens of PD-L1−/− than WT mice produced GzmK or all three Gzms simultaneously." (PMID 30804928, 2019). "However, based on studies in GzmK-/- mice, the contribution of GzmK to overall disease severity in response to infection appears to be less than other immune-secreted proteases (i.e., GzmA)." (PMID 40607408, 2025). "Interestingly, the levels of granzyme K during the acute phase of infection were significantly higher in patients who displayed effective class-switch of DENV-specific antibodies to the Th1-associated isotype IgG3, which was measured in the defervescence phase of disease in longitudinal samples." (PMID 39088280, 2024). "Meanwhile, we observed that certain biomarkers (SLC7A5, PDE4D, CXCR4, PER1, PIK3R1, HBA1, HBB) were elevated during the pre-infection phase (LTBI), while others (SOCS3, GZMK, HIS1H3B) were upregulated in the post-infection phase (ATB)." (PMID 40589756, 2025). "Although granzyme K is not specific to NKT cells, given its importance to their function, we investigated the contributions of NKT cells in immune polarization and infection clearance in mice." (PMID 39088280, 2024). "At 6 d post-infection splenic CD8+ cells were enriched and found to express gzmA, gzmB and gzmK mRNA but not gzmC in wt animals." (PMID 19838298, 2009).
immune dysfunction (5 papers, 2018 to 2023). "C5, which expressed CD8A and CD8B, was distinguished by elevated expression of GZMK, which has been recently described as a hallmark of immune dysfunction in inflammation." (PMID 35483355, 2022). "A subpopulation of age-associated granzyme K- (GZMK-) expressing CD8+ T (Taa) cells have been identified as a source of proinflammatory granzyme K and considered a valuable target for age-linked immune dysfunction." (PMID 36267464, 2022).
bacterial infections (3 papers, 2021 to 2025). "Together, extracellular GzmK contributes directly to the immune response to bacterial infections." (PMID 40607408, 2025). "This is the first time that the role of GzmK in the control of bacterial infection is analysed." (PMID 34815792, 2021). "However, further research is needed to confirm the role of inflammation induced by GzmK in the control of other bacterial infections, which is not the main aim of this work." (PMID 34815792, 2021).
infectious disease (2 papers, 2021 to 2022). A disorder directly resulting from the presence and activity of a microbial, viral, or parasitic agent in humans. "In human infectious diseases, GZMK can activate the protease activated receptor-1 (PAR-1) in endothelial cells and induce the production of inflammatory cytokines (TNF-α, IL-1, and IL-6)." (PMID 36199375, 2022). "Moreover, in human infectious diseases, GZMK has been found to activate protease-activated receptor-1 (PAR-1) in endothelial and fibroblast cells and induce the production of inflammatory cytokines, such as TNF-α, IL1, IL-6, and MCP-1." (PMID 34603038, 2021).
neurologic diseases (2 papers, 2025). "Additionally, since GZMK can be employed by CD4+ and CD8+ T cells along with γδ T cells, a summative effect of multiple cell types producing this enzyme could differentially influence neuroinflammation in various neurologic diseases." (PMID 39744938, 2025).
GZMK also shares sentences with these, for which no sentence is quoted: inflammation (3 papers); allergic asthma (2); Alzheimer disease (2); Crohn disease (2); glioma (2); hepatocellular carcinoma (2); inflammatory skin disease (2); pancreatitis (2); tuberculosis (2); age (1); AIDS (1); amyloid (1); Autoimmunity (1); bovine tuberculosis (1); brain ischemia (1); brucellosis (1); chronic obstructive pulmonary disease (1); chronic pancreatitis (1); cognitive decline (1); coinfection (1); colitis (1); dementia (1); dermatitis (1); digestive system diseases (1); Dyskinesia (1); Encephalopathy (1); endometrial cancer (1); eosinophilia (1); epilepsy (1); esophageal cancer (1).
A further 31 diseases each share a sentence with GZMK in 1 paper.